INS (insulin)
Diseases named in the same sentence as INS in open-access papers (continued):
Sharing a sentence is not in itself a finding about the gene and the disease.
Insulin resistance (continued). "Current treatment strategies are aimed at the amelioration of insulin resistance (diet, exercise, weight loss, and metformin and troglitazone therapy), augmentation of insulin supply (sulfonylurea and insulin therapy), or limitation of postprandial hyperglycemia (acarbose therapy)." (PMID 34007967, 2021). "PTP1B is crucially implicated in the development of insulin resistance; it is a negative regulator of insulin action, by dephosphorylating specific residues of phosphotyrosine (pTyr) of the activated insulin receptor (IR) and, thus, interrupting the signalling pathways mediated by the hormone." (PMID 34677434, 2021). "Given that T1DM is characterized by insulin deficiency and T2DM is hallmarked with insulin resistance, these data might indicate a potential role of insulin sensitivity and resistance in coagulation dysfunction." (PMID 34072487, 2021). "In addition, other studies have shown that curcumin regulates the insulin signaling pathway and thus affects cognitive dysfunction associated with the already mentioned insulin resistance." (PMID 34068096, 2021). "As a collective interpretation of these studies, congenital inhibition of autophagy obstructs adipogenesis and results in enhanced insulin sensitivity due to adipocyte browning, but selective inhibition of autophagy in mature adipocytes causes insulin resistance." (PMID 34336862, 2021). "Furthermore, AnxA2 interacts with galectin-3 at the cell surface, which directly induces cellular insulin resistance and associated inflammation under obese conditions by impairing insulin signaling." (PMID 34681689, 2021). "Interestingly, CAR activation has been shown to improve insulin sensitivity, glucose metabolism, and hepatic lipid accumulation in leptin-deficient ob/ob mice, and to prevent obesity, insulin resistance, and hepatic steatosis in HFD-fed mice." (PMID 35211087, 2021). "Insulin could affect cell growth and alter the invasiveness of breast cancer cells, and insulin resistance has been shown to be associated with increased breast cancer risk." (PMID 34371939, 2021). "In vivo studies exposing excessive insulin to rodent demonstrated insulin resistance, causing T2D." (PMID 34358068, 2021). "Insulin resistance has caused dysfunction in the insulin signaling, which promotes cell apoptosis." (PMID 33672590, 2021). "Type 2 diabetes occurs from relative deficiency of insulin attributed to insulin resistance." (PMID 34307690, 2021). "In addition, obesity-related insulin resistance is associated with impaired insulin-mediated inhibition of lipolysis in adipose tissue (AT), resulting in an increased efflux of free fatty acids (FFAs) into the blood and, consequently, ectopic lipid deposition." (PMID 34630157, 2021). "In addition to insulin resistance, type 2 diabetes is associated with reduced glucose-stimulated insulin secretion and β-cell mass, and reduced insulin resistance compensates for low insulin secretion, promotes β-cell function, and prevents β-cell exhaustion." (PMID 34359426, 2021). "Thus, functional foods that reduce insulin resistance and potentiate glucose-stimulated insulin secretion reduce the risk of type 2 diabetes and cardiovascular diseases." (PMID 34359426, 2021). "A study has showed that skeletal muscle insulin resistance may be caused by impaired insulin signaling pathways in endothelial cells." (PMID 35111067, 2021). "In addition, high levels of branched-chain amino acids (BCAAs) are often associated with increased BMI levels and insulin resistance whereas low levels of BCAAs are accompanied by lower BMIs and good insulin sensitivity." (PMID 34829598, 2021). "Intake of higher EDIH scores (representing more hyperinsulinemic dietary patterns) was associated with greater concentrations of all five insulin response markers, with the percent difference (PD) smallest for glucose (1.3%) and largest for insulin resistance (HOMA-IR, 8.%)." (PMID 34616762, 2021).
Insulin resistance (continued). "Type 2 diabetes may range from predominant insulin resistance with relative insulin deficiency to a predominantly insulin secretory defect with insulin resistance." (PMID 33467194, 2021). "The genes were associated with insulin resistance and insulin secretion." (PMID 34834527, 2021). "For example, insulin signaling might be linked to aging and aging-related diseases in humans, with recent data on metformin (a treatment for insulin resistance) suggesting it may be useful as an anti-aging drug." (PMID 34839356, 2021). "With turn deficiency in IDE might lead to an accumulation of insulin in the brain (hyperinsulinemia), leading to insulin resistance and glucose intolerance." (PMID 33918576, 2021). "However, hyperprogranulinemia present in obesity is associated with insulin resistance and deficient insulin signaling, whereas its deficiency can protect from diet-induced insulin resistance." (PMID 33807959, 2021). "However, the chronic, persistently high, demand for insulin, which occurs during insulin resistance, can lead to progressive dysfunction, and eventual loss, of beta cells." (PMID 34203703, 2021). "Thus, we are the first to show that the degree of EAT adipocytes’ insulin resistance is associated with the severity of atherosclerosis and systemic imbalance of insulin production independently from the size and hypertrophy of adipocytes." (PMID 33440802, 2021). "However, visceral fat accumulation is an important correlate with insulin resistance, and higher circulating endocannabinoids have been associated with insulin resistant obese patients." (PMID 34684760, 2021). "The genetic variants influence insulin secretion and insulin resistance to affect the T2DM risk." (PMID 34834527, 2021). "Furthermore, increased oxidative stress and JNK/MAPK expression can contribute to pancreatic β-cell dysfunction with apoptosis, glucose-induced insulin secretion impairment, and subsequent insulin resistance, which is a key hallmark of type 2 DM54." (PMID 33568752, 2021). "The failure in PI3K pathway activation associated with insulin resistance may occur through different points of the pathway, as the binding of insulin to its receptor or along the signaling cascade." (PMID 33672171, 2021). "In summary, the inability of pancreatic β-cells to produce insulin in IDDM or insulin resistance is implicated in the failure of insulin to perform its function, leading to hyperglycemia, polyuria, weight loss or increase, polydipsia, delayed wound healing, and blurred vision." (PMID 34833928, 2021). "TYK2PV status was determined using direct DNA sequencing and its associations with fasting insulin, C-peptide, and homeostatic model assessment of insulin resistance (HOMA-IR) were evaluated in type 2 diabetes patients without sulfonylurea or insulin medication." (PMID 33799705, 2021). "IL-1β was strongly linked with insulin resistance and impaired insulin secretion." (PMID 34769448, 2021). "Pharmacological approaches that reduce insulin secretion and/or hepatic insulin clearance may be beneficial and prevent the progression to insulin resistance and hyperinsulinemia-associated conditions and diseases." (PMID 34360563, 2021). "Type 2 diabetes (T2D) is a heterogeneous disease with varying clinical presentation and disease progression, in which genetic and environmental factors contribute to progressive loss of adequate insulin secretion, frequently on the background of insulin resistance." (PMID 34502360, 2021). "Insulin resistance: Insulin resistance in the metabolic tissues is often associated with a decreased number of mitochondria and available oxidative enzymes, abnormal mitochondria morphology, reduced production of ATP and insulin-dependent glucose disposal." (PMID 34445477, 2021).
Insulin resistance (continued). "Firstly, the adverse effects of preterm birth may be related to the accelerator hypothesis, which may be plausibly explained by the mechanism that rapid growth increases the demand of insulin secreting and causes β-cell stress and insulin resistance." (PMID 33935963, 2021). "The higher expression of NHE1 may be explained by the high plasma insulin and glucose levels associated with insulin resistance, as insulin and glucose have been observed to increase the activity of NHE1 in human monocytes." (PMID 33426802, 2021). "Pro-inflammatory cytokines, particularly IL-1β, act in an autocrine and paracrine manner to interfere with insulin signaling in adipose tissue, liver, skeletal muscle, and pancreas or induce β-cell dysfunction which leads to insulin deficiency and insulin resistance." (PMID 34017260, 2021). "In the current study, we sought to determine whether risk factors for metabolic insulin resistance would also predict microvascular insulin responses in humans with a large range of insulin action and resistance patterns." (PMID 34075130, 2021). "In addition, serine rather than tyrosine phosphorylation of the insulin response element has been associated with insulin resistance related to decreased activation of downstream insulin-signaling proteins (Copps and White, 2012)." (PMID 34497507, 2021). "The increase in circulating FFA and pro-inflammatory mediators further impairs insulin action in other metabolically active organs and tissues, including skeletal muscle and the liver, leading to systemic insulin resistance, which is associated with impaired glucose transport." (PMID 33920604, 2021). "In our study, however, the women with T1D had poor metabolic control, which is associated with higher insulin resistance and a higher insulin requirement; this may have affected their body composition." (PMID 33353965, 2020). "Previous studies have reported that VDR gene polymorphisms are connected with insulin resistance, which could reflect the changing of insulin sensitivity, and with insulin secretory capacity." (PMID 33383970, 2020). "Excess VF is associated with higher insulin levels and the development of insulin resistance." (PMID 33033231, 2020). "This mutation reduces binding capability to the insulin peptide and results in insulin resistance in the cavefish, which paradoxically may be a trait beneficial to survival in a cave environment lacking a stable food supply." (PMID 33076817, 2020). "Fetuin-A blocks the insulin from attaching to its receptors, creates a pathway and causes insulin resistance, and in this data it indicates that fetuin-A may play a role in pathophysiology of type-II diabetes mellitus." (PMID 32063933, 2020). "Additionally, we recently demonstrated that RSV ameliorated the high insulin-induced skeletal muscle cell insulin resistance, and that these effects were linked to AMPK activation/phosphorylation." (PMID 32664532, 2020). "In order to explore whether this relationship may be attributable to insulin resistance, we used multivariable linear regression models to assess the associations between fasting insulin and HbA1c levels and HOMA-IR scores in participants ≥60 years old." (PMID 33396964, 2020). "Insulin is a neurotrophic factor and loss of this neurotrophic support due to insulin resistance as seen in metabolic syndrome and T2D, is thought to affect PI3K/Akt signaling pathway inside the neurons leading to mitochondrial dysfunction and oxidative stress, thus promoting PN." (PMID 32872256, 2020). "Furthermore, it has been repeatedly reported that oxidative stress is highly correlated with insulin resistance and can also be the cause of poor insulin sensitivity." (PMID 32545342, 2020). "High levels of TNF‐α in the cerebrospinal fluid (CSF) of patients with AD indicate that inflammation‐induced impaired brain insulin signaling may be a major cause of insulin resistance observed in these patients." (PMID 32170854, 2020).
Insulin resistance (continued). "Furthermore, we identified sphingosine as a chief inhibitor of hepatic insulin signaling, which primarily accounts for the SphK2 deficiency-induced insulin resistance." (PMID 32917816, 2020). "Additionally, elevated arachidonic acid levels during glucose-induced insulin release were previously shown to trigger further increases in insulin secretion, potentially increasing risk of insulin resistance." (PMID 32972433, 2020). "Overall, these data indicated that inhibition of SphK2 could be an attractive target to develop treatments to ameliorate insulin resistance but also insulin secretion associated with obesity and T2D." (PMID 32849282, 2020). "Moreover, insulin resistance due to high insulin level is also associated with an increased inflammatory condition, including elevated CRP." (PMID 32872655, 2020). "Indeed, insulin resistance which is the defect underlying prediabetes, T2D and gestational diabetes, always involves altered insulin-mediated glucose uptake." (PMID 33665204, 2020). "Immunosuppressive regulatory T cells (Tregs), phagocytic M2-like macrophages, and innate lymphoid cells type 2 (ILC2) control lean AT inflammation to maintain systemic insulin sensitivity, while the loss of these cells in obesity leads to AT inflammation and insulin resistance (IR)." (PMID 32774894, 2020). "Insulin is known to act on several metabolic pathways, including lipid metabolism and there are evidences that high blood triglycerides concentration is associated with insulin resistance." (PMID 31900155, 2020). "Increased hepatic insulin resistance is associated with hyperinsulinemia, which consequently increases triacylglycerol acylation and reduces lipolysis in adipose tissue, where fat mobilization is strongly inhibited by insulin." (PMID 32580324, 2020). "Furthermore, miR-125a enhances insulin signaling and when it significantly downregulated it associated with insulin resistance in IR-3T3-L1 adipocytes." (PMID 32366215, 2020). "While much recent research has aimed to delineate the precise cause(s) of obesity-associated T2DM, the primary mechanism is believed to be insulin resistance that derives from white adipose tissue, liver, and/or skeletal muscle, accompanied by impaired insulin secretion by pancreatic β-cells." (PMID 32158768, 2020). "T2DM, metabolic syndrome and obesity are characterized by the insulin resistance and the impairment in the insulin secretion which both are tightly associated with the impairment in the adipose tissue functions, and increased levels of reactive oxygen species (ROS) termed as oxidative stress." (PMID 33746608, 2020). "Obesity is closely associated with the inability to respond to insulin, termed insulin resistance." (PMID 32463116, 2020). "Partitioned polygenic scores have been developed by assigning subsets of variants to specific pathophysiological categories, such as insulin resistance, adiposity, or insulin secretion, and proposed as a tool to enable classification of patients to specific disease subtypes." (PMID 33033935, 2020). "The REE was strongly associated with age, BMI, insulin, and insulin resistance." (PMID 32651404, 2020). "In T2DM rats, lower insulin levels and insulin resistance may be an important cause of reduced glucose uptake in skeletal muscle." (PMID 32647998, 2020). "Additionally, butyrate minimises the risk of development of insulin resistance as it improves insulin signalling." (PMID 33086688, 2020). "The pathogenesis of T2DM is linked to insulin-resistance, which leads to a slow decline of pancreatic β-cells; both pathological states influence each other and, presumably, synergistically exacerbate diabetes inducing the failure of insulin over time." (PMID 33187372, 2020). "Insulin normally induces ammonia synthesis in tubules, but it may be ineffective if immunosuppressive agents cause insulin resistance in transplant recipients." (PMID 33261165, 2020).
Insulin resistance (continued). "However, a study focused on cardiometabolic risk reported a decrease in the level of insulin and insulin resistance in pregnant women consuming higher amounts of isoflavones." (PMID 32824177, 2020). "Whether altered MAM integrity leads to insulin resistance or whether impaired insulin signaling disrupts MAM functions, and which factor is causal, remains to be determined." (PMID 33329397, 2020). "Moreover, murine Fxr deficiency results in insulin resistance and impaired glucose tolerance, whereas its activation improves insulin sensitivity." (PMID 32661285, 2020). "Moreover, the abundance of CLS in adipose tissue is associated with insulin levels, insulin resistance, and type 2 diabetes." (PMID 32630445, 2020). "Previous research indicated that the increase of inflammatory cytokines could cause insulin resistance by influencing the phosphorylation of IRS in insulin signal transduction." (PMID 33329383, 2020). "Therefore, a mother who develops GDM manifests similar metabolic disturbances to T2DM, which is characterized by insulin resistance and insulin signalling deficiency." (PMID 32697764, 2020). "BMI-independent associations included correlations among insulin resistance-related factors (insulin, C-peptide, glucose, and glucose tolerance, r = 0.3 to 0.7), blood lipids (cholesterol and triglycerides, r = 0.3), and blood pressure (systolic and diastolic blood pressure, r = 0.7)." (PMID 32210264, 2020). "Proinflammatory adipokine profile is associated with obesity and is thought to promote insulin resistance, while adiponectin and other anti-inflammatory adipokines are reduced in obesity and therefore might contribute to the maintenance of insulin sensitivity." (PMID 31963662, 2020). "In pregnant women with PCOS, both the physiologic state of hyperinsulinemic insulin resistance and early abnormal insulin action could worsen the insulin resistance, which significantly increase the risk of GDM." (PMID 33353136, 2020). "Therefore, ER stress can increase the risk of insulin resistance in aging skeletal muscle by directly impairing insulin signaling or activating the JNK pathway." (PMID 32082422, 2020). "As insulin is critical for cellular glucose uptake and to prevent efflux of fat from the adipose tissue, also known as lipolysis inhibition, children with insulin resistance are at risk of developing type 2 diabetes and cardiovascular complications at an earlier age." (PMID 33266497, 2020). "As pathological insulin resistance is viewed as a driving force of T2D development, now, we present evidence that the molecular and cellular metabolic disturbances associated with OA are linked to an insulin-resistant state similar to T2D." (PMID 32566279, 2020). "The relationship between the chemerin and insulin resistance/insulin sensitivity is not completely understood; some studies report a direct association with insulin resistance, while others refute it, saying that chemerin is actually involved in the regulation of insulin sensitivity." (PMID 32858998, 2020). "Studies have been conducted through dexamethasone/corticotrophin‐releasing hormone (DEX/CRH) test and insulin resistance evaluated by the homeostasis model assessment of insulin resistance (HOMA‐R) to demonstrate that HPA axis dysfunction is associated with insulin in patients with depression." (PMID 32281722, 2020). "Nonetheless, it may be that exercise has a greater impact on postprandial glucose, which is more strongly linked to muscle insulin resistance, whereas fasting glucose is believed to be more strongly associated with hepatic insulin resistance." (PMID 32849285, 2020). "Elevated insulin can be a cause and consequence of obesity and insulin resistance." (PMID 32860984, 2020).